CFH (complement factor H)
Diseases named in the same sentence as CFH in open-access papers (continued):
Sharing a sentence is not in itself a finding about the gene and the disease.
nephritis (4 papers, 2011 to 2025). Inflammation of renal tissue. "Taken together, SLE and SLE nephritis do not appear to be associated with frequent mutations in CD46 or CFH as reported for some other kidney diseases, but these mutations are likely to affect the year of onset of nephritis." (PMID 22171659, 2011). "Mutations found in CD46 and CFH were found to affect the age at onset of nephritis in the analyzed SLE patients." (PMID 22171659, 2011). "Within the nephritis group, CFH concentrations were the lowest in those classified as having moderate nephritis (median: 334.56 ng/mL, IQR: 178.86), a level significantly below that of the control group (p < 0.05)." (PMID 40868541, 2025). "In the present study we performed Sanger sequencing of all exons in the CD46 and CFH genes in two cohorts of SLE patients collected in southern and mid Sweden to identify rare variants with a potential effect on SLE and SLE nephritis." (PMID 22171659, 2011). "The exons of complement inhibitor genes CD46 and CFH (factor H) were fully sequenced using the Sanger method in SLE patients with nephritis originating from two cohorts from southern and mid Sweden (n = 196)." (PMID 22171659, 2011). "The median age of nephritis onset in the SLE patients carrying CD46 and CFH mutations in the combined cohorts was 24 years (range 12 to 51) compared with 32 years (range 9 to 84) in the patients free of the mutations." (PMID 22171659, 2011). "The presence of mutations in CD46 and CFH did not predispose to SLE or nephritis but was associated with earlier onset of nephritis." (PMID 22171659, 2011). "We found nonsynonymous, heterozygous mutations in CFH in 6.1% patients with nephritis, in comparison with 4.0% and 5.4% in patients without nephritis and controls, respectively." (PMID 22171659, 2011). "Both the nephritis subgroup (median: 336.53 ng/mL, IQR: 181.32) and the non-nephritis subgroup (median: 430.21 ng/mL, IQR: 306.60) had significantly reduced CFH levels in comparison to the controls (p < 0.05 for both)." (PMID 40868541, 2025).
pulmonary TB (4 papers, 2019 to 2025). "When the concentrations of the six available markers (CRP, IFN-γ, IP-10, CFH, Apo-A1, and SAA), from the adult pulmonary TB seven-marker signature were evaluated in serum samples from children with TBM vs. those without TBM individually, significant differences were obtained for CFH only." (PMID 31612118, 2019).
schizophrenia (4 papers, 2021 to 2023). A major psychotic disorder characterized by abnormalities in the perception or expression of reality. "We previously found that schizophrenia patients have higher levels of CFH expression in brain than healthy subjects, and CFH is associated with severity of negative symptoms in schizophrenia." (PMID 37520223, 2023). "We hypothesized that CFH may be a potential biomarker of anhedonia in schizophrenia and the effect of olanzapine in alleviating anhedonia may be through modulating the expression of CFH." (PMID 37520223, 2023). "However, we have recently found that the gene encoding CFH (CFH) influences negative symptoms in schizophrenia." (PMID 37520223, 2023). "Our results showed that plasma level of CFH is significantly higher in schizophrenia patients with anhedonia than those without anhedonia." (PMID 37520223, 2023). "As such, we tested the inflammatory marker CRP, and complement system including C3, C4 and CFH between schizophrenia patients with or without anhedonia." (PMID 37520223, 2023).
Stroke (4 papers, 2012 to 2023). Sudden impairment of blood flow to a part of the brain due to occlusion or rupture of an artery to the brain. "The LCN2-decreasing CFH variants reported here were found by MR to causally reduce blood pressure, body mass index and waist-to-hip ratio, but increase risk of stroke, triglycerides and LDL levels." (PMID 37778719, 2023). "Possible common mechanisms for the link between AMD and stroke include, but are not limited to, the complement factor H gene and complement cascade activation in atherosclerotic lesions." (PMID 38983510, 2022).
Thrombocytopenia (4 papers, 2016 to 2025). A reduction in the number of circulating thrombocytes. "One of our aHUS cases with a novel complement factor H mutation, who developed unusual laboratory findings (thrombocytopenia and mild creatinine elevation without other features of TMA) following discontinuation of eculizumab was presented." (PMID 27495036, 2016). "Interestingly, we documented retrospectively a second “silent” rise of plasma sC5b-9 concentrations long after the resolution of TTP, without apparent hemolysis and thrombocytopenia and in the absence of anti-CFH autoantibodies." (PMID 29728803, 2018).
asthma (3 papers, 2012 to 2024). "Despite observed heterogeneity, a consistent result was found in the elevation of complement regulatory proteins, such as complement Factor H, in samples from patients with asthma compared to those from healthy subjects." (PMID 38892755, 2024).
coronary heart disease (3 papers, 2007 to 2025). "Using samples from the Atherogene and ECTIM studies, Nicaud and colleagues were also unable to find any association between common polymorphisms in the CFH and coronary artery disease." (PMID 17877809, 2007). "This study was designed to investigate if, using a family-based approach, there was an association between genetic variants of the CFH gene and risk of early-onset coronary heart disease." (PMID 17877809, 2007). "Likewise, in their study of 1170 patients with angiographically confirmed coronary artery disease and 560 controls, Goverdhan and co-workers did not detect any association between the CFH Y402H gene variant and presence or severity of CAD." (PMID 17877809, 2007).
endometriosis (3 papers, 2022 to 2025). The growth of functional endometrial tissue in anatomic sites outside the uterine body. "The serum levels of adipsin and complement factor- H(CFH) were found to be significantly increased in women with endometriosis." (PMID 40692689, 2025). "The roles of C7, CFH, and FZD7 in endometriosis have been reported previously." (PMID 36339397, 2022).
glioblastoma (3 papers, 2019 to 2024). The most malignant astrocytic tumor (WHO grade IV). "Further, increased expression levels of CFH and FHL-1 levels were associated with poorer survival in glioblastoma patients." (PMID 38389705, 2024).
hyperlipidemia (3 papers, 2013 to 2015). "The most predictive disease model for exudative AMD included age, spherical equivalent, smoking, CFH rs800292, and ARMS2 rs10490924 while that for typical CNV included age, hyperlipidemia, spherical equivalent, and ARMS2 rs10490924." (PMID 26171855, 2015).
inflammatory bowel disease (3 papers, 2023 to 2025). A spectrum of small and large bowel inflammatory diseases of unknown etiology. "For example, in the LCN2/CFH interaction, expression of the former is observed in kidney and liver injury, lung inflammation and Inflammatory bowel disease-positive intestinal epithelium." (PMID 37778719, 2023).
kidney damage (3 papers, 2019 to 2025). "However, the exact mechanism behind the development of nephropathies upon CFH deficiency has not yet been addressed." (PMID 31354740, 2019). "Though increasing evidence supports the role of complement in proteinuria-mediated kidney damage, plasma CFH protein level is not correlated with UPCR or eGFR in this study, most likely because most children with CKD are still in the early stages." (PMID 35740418, 2022).
kidney failure (3 papers, 2014 to 2025). An acute or chronic condition that is characterized by the inability of the kidneys to adequately filter the blood. "Anti-CFH Ab-associated HUS has serious clinical manifestations, with a mortality rate of up to 25%, and 20–29% of survivors progress to kidney failure; the recurrence rate of anti-CFH Ab-associated HUS is approximately 20–25%." (PMID 35730179, 2022).
leukemia (3 papers, 2014 to 2025). A malignant (clonal) hematologic disorder, involving hematopoietic stem cells and characterized by the presence of primitive or atypical myeloid or lymphoid cells in the bone marrow and the blood. "For the human disease gene orthologs, we found 102 CNVRs identified in the study overlapped 210 genes associated with human diseases, such as Stiff skin syndrome, Leukemia, polycythemia vera, autism, and Complement factor H deficiency." (PMID 25023178, 2014). "The upregulated expression of CFH might be beneficial to confront VEGF produced by ALL cells, as VEGF has been proved to promote leukemia cell infiltration into CNS." (PMID 31186631, 2019). "Although the precise mechanism through which CFH regulates the immune response of leukemia cells is not fully elucidated, we can infer from these studies that CFH may serve as a prognostic marker for AML and may even have the potential to become a novel therapeutic target." (PMID 41163355, 2025).
liver cancer (3 papers, 2017 to 2023). An epithelial or non-epithelial malignant neoplasm that arises from the liver. "However, recent reports suggest that, C7 are highly expressed in HCC tissues, and C7 combined with CFH protein control the stemness of liver cancer cells via LSF-1." (PMID 29262557, 2017).
melanoma (3 papers, 2018 to 2023). A malignant, usually aggressive tumor composed of atypical, neoplastic melanocytes. "In this immunotherapy research, CFH mutations exhibited the benefits of both the response rate and survival interval in male melanoma patients." (PMID 34795662, 2021). "Similar to the mouse melanoma model data, the S1 population (PDGFRAhi PDPNhi CD34hi) was characterized by the expression of genes involved in the regulation of immune cell recruitment (cytokines: CXCL12; complement factors: CFD, C3, C1S, CFH)." (PMID 36929873, 2023).
Retinal dystrophy (3 papers, 2019 to 2025). Retinal dystrophy is an abnormality of the retina associated with a hereditary process. "Ten families had variants in genes related to a syndromic disease with retinal dystrophy (COL9A1, CEP290, PCDH15, LRP5, PEX1, CFH, COL2A1 and COL11A1)." (PMID 35457050, 2022). "Of these patients, seven had monoallelic pathogenic variants in ABCA4, one had biallelic variants of uncertain significance (VUS) in ABCA4, two had monoallelic VUS in ABCA4, and eight harbored VUS in other retinal dystrophy-related genes, including KCNV2, RIMS1, CRB1, CFH, RP1L1, UNC119, and SEMA4A." (PMID 41234456, 2025).
allergic reaction (2 papers, 2020 to 2022). "Elevated CFH causes C3a and C5a to decrease and, as a result, inhibits the allergic reaction and suppresses allergens other than cedar." (PMID 36365030, 2022).
anemia (2 papers, 2018 to 2023). A reduction in the number of red blood cells, the amount of hemoglobin, and/or the volume of packed red blood cells. "Severe anemia was observed in patients with CFH variants (38%), while C3 levels varied depending on complement abnormalities: indeed, half of the patients with C3 and MCP variants and 89% of the patients with anti-CFH antibodies showed decreased levels of C3." (PMID 37833944, 2023).
Atrophy (2 papers, 2015 to 2017). Any weakening or degeneration, especially through lack of use. "There was a strong association between drusen area, volume and RPE atrophy in the macula with risk alleles in CFH (rs12038333) and SYN3 (rs5749482)." (PMID 25893111, 2015).
cataract (2 papers, 2023 to 2024). Partial or complete opacity of the crystalline lens of one or both eyes that decreases visual acuity and eventually results in blindness. "Within the male cohort, three complement proteins (CLU, C6, and CFH) were downregulated in POAG patients compared to those with cataracts." (PMID 37763167, 2023). "The results revealed decreased levels of complement component C8 gamma chain (C8G) (FC = 0.83, p = 0.026), complement C6 (FC = 0.81, p = 0.032), and complement factor H (CFH) (FC = 0.77, p = 0.024) in POAG subjects relative to those with cataracts." (PMID 37763167, 2023).
depression (2 papers, 2020 to 2024). "CFH was among the genes mapped in brain tissues to depression risk SNPs in our female risk cluster, and also has shown a genetic association with MDD in a former study." (PMID 38589364, 2024).
fatty liver disease (2 papers, 2020 to 2025). A reversible condition wherein large vacuoles of triglyceride fat accumulate in liver cells via the process of steatosis. "Therefore, low CFH expression might contribute to the harmful effects of lipid peroxidation products in fatty liver disease." (PMID 33362721, 2020). "Further molecular and genetic studies are needed to elucidate the involvement of CFH and CFHR proteins in relation to OSE recognition during fatty liver disease." (PMID 33362721, 2020).
Glomerular sclerosis (2 papers, 2023 to 2024). Accumulation of scar tissue within the glomerulus. "High abundance of urinary CFH and CFHR2, two members of the alternative pathway, is closely associated with glomerulosclerosis and TIF." (PMID 37020564, 2023).
HELLP syndrome (2 papers, 2022 to 2025). A life-threatening condition that can potentially complicate pregnancy. "Finally, in certain configurations of the collapsed glycocalyx, activation of the alternative complement pathway through dysregulation of CFH and C3b may explain the development of HELLP syndrome." (PMID 40746214, 2025).
keratitis (2 papers, 2020 to 2024). A corneal disease that is characterized by inflammation of the cornea. "Previous mass spectrometry data show the presence of CFH, the major negative regulatory factor of the alternative complement pathway, in keratitis patient's tear." (PMID 32435625, 2020). "The protein band corresponding to 180 kDa co-migrating with purified CFH showed the presence of CFH in keratitis patients' tear but not in control tear." (PMID 32435625, 2020).
macular dystrophies (2 papers, 2008 to 2016). "Of note, 9 of the 12 carriers of a rare CFH variant in these families had similar phenotypic appearances in both eyes, a characteristic trait of monogenic ocular diseases and macular dystrophies." (PMID 27572114, 2016).
malaria (2 papers, 2019 to 2023). Malaria is a serious and sometimes fatal disease caused by a parasite that commonly infects a certain type of mosquito which feeds on humans. "The increased levels of Complement Factor H were correlated with severity biomarkers and susceptibility in severe malaria cases." (PMID 37628675, 2023). "This is in line with previous reports showing that blood proteins such as apolipoprotein E, serum amyloid A, LPS binding protein, complement factor H, albumin, and fibrinogen that were found to be elevated in malaria individuals are able to bind to HZ." (PMID 31905972, 2019).
Meniere disease (2 papers, 2014 to 2020). A disease of the inner ear (labyrinth) that is characterized by fluctuating sensorineural hearing loss; tinnitus; episodic vertigo; and aural fullness. "There is also a tendency toward Meniere’s disease or vertigo-specific biomarkers, namely beta-2 glycoprotein, beta-actin, complement factor-H, and vitamin D binding protein." (PMID 33383894, 2020). "Proteins related to immune reaction or inner ear disorder such as complement factor H, β2 glycoprotein 1, vitamin D binding protein, and β actin were previously reported to be increased in the serum of Meniere's disease by proteomic analysis." (PMID 25330336, 2014).
meningococcal meningitis (2 papers, 2019 to 2020). "For meningococcal meningitis, loci within the complement factor H (CFH) gene and CFH-related protein 3 (CFHR3) in the host were associated with susceptibility to disease." (PMID 33262994, 2020).
myopia (2 papers, 2021 to 2023). "Based on our results, ARMS2 (rs10490924) and CFH (rs1061170) SNPs are associated with response to ranibizumab in high myopia patients with CNV." (PMID 34834388, 2021).
osteosarcoma (2 papers, 2025). A usually aggressive malignant bone-forming mesenchymal neoplasm, predominantly affecting adolescents and young adults. "In our study, we observed reduced expression of CFH in the metastatic group, and we believe that CFH plays a significant role in the imbalance of the complement and immune systems in osteosarcoma." (PMID 40276062, 2025). "First, we identified MAPK1, CFH, ATG7, and DDIT4 as independent prognostic factors in osteosarcoma patients via Cox regression analysis." (PMID 40276062, 2025).
pancreatic ductal adenocarcinoma (2 papers, 2017 to 2023). An infiltrating adenocarcinoma that arises from the epithelial cells of the pancreas. "It was reported that the occupancy changes of N-glycosylation site, such as NET and NVT of complement factor H, were associated with pancreatic ductal adenocarcinoma and chronic pancreatitis." (PMID 28736531, 2017).
periodontitis (2 papers, 2022 to 2025). An acute or chronic inflammatory process that affects the tissues that surround and support the teeth. "The multiple linear regression revealed that elevated DKK-3 protein levels were linked to increased DKK-3 (rs11544817) expression and decreased CFH (rs10737680) expression, indicating a higher risk for periodontitis and CAD." (PMID 41356214, 2025). "The multiple linear regression revealed that elevated DKK-3 protein levels were associated with increased DKK-3 (rs11544817) expression and decreased CFH (rs10737680) expression, indicating a higher risk for periodontitis and CAD." (PMID 41356214, 2025). "As MMP‐8 is centrally involved in the pathogenesis of periodontitis, we aimed to evaluate the presence of genetic polymorphisms of S100A8/A9/A12, MMP8, and CFH in periodontitis." (PMID 35315933, 2022). "The aim of our study was to evaluate the presence of S100A8/A9/A12, MMP8, and CFH polymorphisms in periodontitis and to find out if polymorphisms of these genes affect the concentrations of corresponding proteins or marker of complement activation in saliva." (PMID 35315933, 2022). "Thus, these common polymorphisms of CFH were associated with decreased symptoms of periodontitis and lower risk of having periodontitis." (PMID 35315933, 2022). "The study found elevated DKK-3 (rs11544817) and reduced CFH (rs10737680) protein levels and gene expression in patients with periodontitis and CAD, suggesting that these genes regulate their respective proteins." (PMID 41356214, 2025). "This study analyzed the DKK-3 and CFH protein levels in the subgingival plaque and gene expression in the subgingival tissue of patients with periodontitis and CAD." (PMID 41356214, 2025). "Polymorphisms of S100A9 or MMP8 did not associate with any periodontal parameters, whereas polymorphisms in CFH gene as well as saliva TCC concentrations were associated with clinical and radiographic signs of periodontitis." (PMID 35315933, 2022). "Among the studied polymorphisms of CFH, MMP8, and S100A8/S100A9/S100A12 gene region, those located in the CFH gene associated with periodontitis, whereas the ones near S100A9 or in the MMP8 gene did not." (PMID 35315933, 2022). "Significant findings were obtained when comparing DKK-3 and CFH proteins at baseline and at day 90, suggesting that higher DKK-3 levels and lower CFH protein levels are correlated with the severity of periodontitis and higher lipid profiles." (PMID 41356214, 2025). "This study provides the first evidence of DKK-3 and CFH protein expression in subgingival plaque and tissue samples from patients with periodontitis with or without CAD compared to healthy controls." (PMID 41356214, 2025). "However, the gene expression of DKK-3 (rs11544817) and CFH (rs10737680) and their protein levels in patients with periodontitis and CAD following non-surgical periodontal therapy (NSPT) have not been explored." (PMID 41356214, 2025).